SMAD2 (SMAD family member 2)
Diseases named in the same sentence as SMAD2 in open-access papers (continued):
Sharing a sentence is not in itself a finding about the gene and the disease.
tumor (continued). "Smad2 is overexpressed in CRC cancer tissue as compared to normal colorectal mucosa, and plays an important role in promoting tumor progression." (PMID 25980495, 2015). "In a mouse model of bone metastasis, Smad2 knockdown in MDA-MB-231 cells resulted in significantly faster tumour establishment in bone compared to the parental cell line, suggesting a tumour suppressive role." (PMID 25884855, 2015). "Immunoblotting analyses showed that phosphorylated MEK and ERK compared to total ERK, as well as phosphorylated SMAD2/3 compared to total SMAD2/3 and SMAD4, were increased both in SNORD113-1 siRNA transfected HepG2 cells and in HCC tumor tissues." (PMID 25217841, 2014). "Interestingly, a number of genes that change their expression in immortalized cells, e.g. PI3K, MDM2, SMAD2/3 and STAT1, are implicated in the evasion of apoptosis and acquisition of insensitivity to growth-inhibiting signals, which are characteristic features of tumour cells." (PMID 24371281, 2014). "Accordingly, in this study, we examined the expression of TGF-β1, Smad2, phospho-Smad2 (p-Smad2), Smad3, phospho-Smad3 (p-Smad3), Smad4, and Smad7 in normal anterior pituitaries, invasive NFPAs, and noninvasive NFPAs and evaluated whether they were correlated with tumor development and invasion." (PMID 24636138, 2014). "In this model, the SMAD2/3 and STAT3 signaling pathways are activated in tumor cells as shown using CHLA-255 SMAD2/3 and STAT3 Fluc reporter cell lines, and activation is inhibited by lenalidomide." (PMID 23982484, 2013). "Our data strongly suggest that the shift between tumor suppressive and tumor promoting TGF-β effects involves different regulation of Smad3 dependent transcription, TβRI expression, Smad2 signaling duration, and endogenous TGF-β/Smad7/TβRII levels." (PMID 23991075, 2013). "Reduced Smad2 expression in RCC correlates with a higher tumor grade, which is indicative of a more aggressive tumor." (PMID 23202921, 2012). "In summary, these data suggest that TGF-β from tumor exosomes interacts with TGF-β receptor on hucMSCs, leading to the sequential activation of Smad2/3 and p38 in hucMSCs." (PMID 23285052, 2012). "CoCM induced higher Smad3- and Smad2-mediated luciferase activity than did TuCM, FbCM, or medium, demonstrating that CoCM derived TGF-β increases TGF-β signaling in tumor cells." (PMID 20352126, 2010). "This is the first report demonstrating that peripheral CRF, at least in part, mediates the tumor-promoting effects of stress and implicates CRF in SMAD2 and β-catenin expression." (PMID 20875132, 2010). "To functionally examine the role of Smad2 activation in PC3 cells, we tested if targeted Smad2 knockdown had any effect on tumor cell invasion." (PMID 19956729, 2009). "CITED2, on the other hand, interacts with Smad2 and Smad3 to induce expression of the matrix metalloproteinase 9 gene in TGF-β-mediated tumor cell invasion." (PMID 19883516, 2009). "For example, bitransgenic MMTV-neu/MMTV-TGF-β1 mice exhibited higher levels of circulating tumor cells and lung metastasis than the MMTV-neu mice and the tumors from the bigenic mice had higher levels of vimentin as well as activated Smad2, Akt, and MAPK." (PMID 16457687, 2005).
tumor (continued). "Furthermore, research has shown that tumor cells activate neutrophils via TGF-β1, leading to the production of the metabolism-regulating signaling molecule FAM3C through Smad2/3 signaling." (PMID 40387965, 2025). "On the contrary, cells with active SMAD2/3/4 undergo apoptosis and cell cycle arrest regardless of the stage of the tumour cell." (PMID 40820091, 2025). "Finally, the levels of genes involved in the tumor EMT, such as CDH2, CDH11, SMAD2, SMAD3, WNT9A, and SP-1, were significantly downregulated after the SH intervention." (PMID 41444284, 2025). "Preclinical studies suggest, that during tumor progression, key components of the canonical TGF-β pathway (e.g., SMAD2/3, SMAD4, TGFBR1/2) are often epigenetically downregulated via histone modifications, potentially leading to non-canonical pathway activation with pro-tumorigenic signaling routes." (PMID 40488800, 2025). "Furthermore, pathways involved in tumour invasiveness and metastasis were also connected and presented in pLN+ OSCC, including clusters named ‘MET promotes cell motility’ and ‘SMAD2/SMAD3:SMAD4 heterotrimer regulates transcription’." (PMID 40038875, 2025). "Specifically, recurrent alterations in transforming growth factor beta receptor type 2 (TGFBR2), SMAD family member 2 (SMAD2), and SMAD family member 4 (SMAD4) genes were detected, potentially impairing TGF-β signalling and underscoring the role of immune dysregulation in tumour biology." (PMID 41465261, 2025). "Therefore, this study aimed to clarify the clinicopathologic significance of periostin and Smad2/3 expression in CRC, with a particular focus on the tumor microenvironment." (PMID 39941916, 2025). "Additionally, our investigation into the phosphorylation status of SMAD2–3 and TAK1 across various cellular subsets revealed a distinct regulatory mechanism in tumor-infiltrating ILC1-like cells." (PMID 41268557, 2025). "Our results revealed that sja-let-7 mimics led to a significant downregulation of TGF-β, TGF-βR1, and SMAD2, while the antagonist SMAD7 was upregulated, suggesting that the anti-tumor effects of sja-let-7 may involve modulation of the TGF-β/SMAD pathway." (PMID 39336756, 2024). "Seven genes passing these filters were involved in various aspects of tumour biology, including cell survival and DNA repair (CASP9, NDRG1, and XPA), mTOR signalling (TSC1), and transcription and RNA processing (ETV6, ISY1, and SMAD2)." (PMID 39660592, 2024). "CHI3L1 may promote tumor growth and migration by interacting with TGF-β1 and TGFR, thereby activating the SMAD2/SMAD3 signaling pathway." (PMID 38177294, 2024). "Smad molecules, such as R-Smads (Smad2, Smad3) and Co-Smad (Smad4), are central mediators of the canonical TGF-β pathway and play critical roles in effectuating TGF-β-mediated EMT, leading to tumor progression." (PMID 39518973, 2024). "This suggests that Smad2 deletion itself is not tumorigenic, but accelerates the malignant progression of tumors, indicating that Smad2 has a tumor-suppressive function." (PMID 38569937, 2024). "SMAD2 and SMAD3 are the main downstream effectors of TGF-β, and despite their 84% protein sequence homology and similar activation patterns, there is growing evidence that SMAD2 and SMAD3 play different and opposing functions including cell invasion, tumour growth, and metastasis." (PMID 37685308, 2023). "In vehicle‐treated and SB‐431542 treated Bmal1+/+CRC tumor–bearing mice, there was no elevated expression of p‐Smad2." (PMID 37330661, 2023). "In a canine transferrable tumor model, tumor-derived TGF-β impairs DCs’ maturation, which may be reversed by IL-6 through Smad2/3 nuclear translocation interference." (PMID 37205317, 2023).
tumor (continued). "They showed that miR-200b-3p can target against zinc finger E-box-binding homeobox 1/2 (ZEB1/2), microfibril-associated glycoprotein 2 (MAGP2), mothers against decapentaplegic homolog 2 (SMAD2) and high mobility group box 3 (HMGB3), thereby inhibiting tumor growth, apoptosis and cellular mobility." (PMID 37705067, 2023). "TGF-β1 could regulate the chemoresistance of tumor cells through complex mechanisms, such as inducing epithelial-mesenchymal transition, increasing the expression of MDR-related genes, and activating Smad2/3 and FOXC1 pathways." (PMID 36641471, 2023). "Likewise, injection of ApoSQ inhibited the activation of migration- and invasion-related signaling pathways, including the Smad2/3, FAK, ERK, and Akt pathways, as well as the protein expression of MMP2 and MMP12 in CD326+ tumor cells." (PMID 36241874, 2022). "Subsequently, p-Smad2 and p-Smad3 enter the nucleus to regulate the transcription and expression of corresponding target genes, which induce the EMT and enhance the migration and invasion of tumor cells in the final." (PMID 35578690, 2022). "On the other hand, MMP-9/MMP-2 protein expression may be downregulated by inhibiting the activation of Smad2/3 (pSmad2/3), thereby inhibiting the occurrence of EMT and weakening the metastatic ability of tumor cells." (PMID 35936728, 2022). "Western blotting demonstrated that LY2109761 not only effectively reduced the phosphorylation of Smad2/3 but also prevented their nuclear translocation, indicating that the upregulation of the TGF-β signaling in tumor cells induced by M2-MDE coculture was successfully inhibited." (PMID 35637794, 2022). "Interestingly, Recent studies show that the biological function of SMAD3 opposes that of SMAD2 in tumor metastasis, and silencing SMAD2 promotes tumor metastasis, whereas SMAD3 KO inhibits tumor metastasis." (PMID 35085106, 2022). "FBXW7 is a tumor suppressor and regulates the TGF-β/BMP-pathway by targeting for degradation co-repressor TGF-β-induced factor 1 (TGIF1), which recruits specific repressor complexes to SMAD2." (PMID 35805024, 2022). "Moreover, YAP was enriched at the promoter regions of several key factors involved in the stemness of tumor cells, such as SOX9, SMAD2/4, OLIG2, and MYC." (PMID 35322024, 2022). "SMAD2 knockdown effectively increases this effect of SMAD3/4, and inducing the transcription of SMAD7 may prevent TGF-β-induced EMT of tumor cells; thus, SAMD7 and SAMD2 may play a role in EMT to regulate tumor metastasis." (PMID 34367975, 2021). "Collectively, SGK1 expression was upregulated by the PI3K pathway activated by ligation of Dex and GR, and then SGK1 phosphorylated Nedd4l, which led to Smad2 release from the suppressive Nedd4l-Smad2 complex, and subsequent upregulation of CTGF, which finally promoted tumor metastasis." (PMID 34272474, 2021). "The results indicated that the regulations of P-AKT, P-PI3K, Smad2, Smad3, P-JNK, P-ERK, and NF-κB expressions may be involved in resveratrol enhances anti-tumor of cisplatin in MDA231 xenografts." (PMID 33921192, 2021). "Our experiments demonstrated BBR increased p-Smad2 and decreased p-Smad3 by binding to TGFβR1 and TGβFR2 inhibiting TGF-β/Smad, then, PI3K/AKT and other signaling pathways to restrain EMT, metastasis, and invasion in tumor cells." (PMID 34712379, 2021). "Indeed, it has been previously reported that TME-induced TGF-β1 expression in CRC cells in a Smad2-dependent process, and it is known to play a major role in TGF-β1-induced tumor progression, migration, and EMT." (PMID 34276382, 2021). "Furthermore, CCL22 promoted Treg recruitment to the tumor site; the Tregs then secreted TGF-β, which in turn promoted L1CAM expression via Smad2/3 in a positive feedback loop." (PMID 33710805, 2021).
tumor (continued). "In vivo, resveratrol enhanced tumor growth inhibition and reduced body weight loss and kidney function impairment by cisplatin in MDA231 xenografts, and significantly reduced the expressions of P-AKT, P-PI3K, Smad2, Smad3, P-JNK, P-ERK, and NF-κB in tumor tissues (p < 0.05)." (PMID 33921192, 2021). "Recent studies have demonstrated that miR-27a by regulating SMAD2 inhibits tumor growth and migration by interrupting TGF-β signaling, ultimately leading to inhibition of cancer cell proliferation, induction of apoptosis, and decreased tumor cell migration." (PMID 33916931, 2021). "TGFβ signaling inhibition with galunisertib results in a reduction of phosphorylated SMAD2 in tumor cells, but not a survival improvement." (PMID 34867089, 2021). "In addition, SMAD2/3, as an intracellular signal transduction molecule in the TGF-β pathway, is phosphorylated after the action of TGF-β, leading to tumor formation." (PMID 33937030, 2021). "By performing differentially expressed gene (DEG) analysis, we found that many immunosuppressive and exhaustion-related genes such as LAG3, CD101, SMAD2, and ID1, which was one type of the mediators of tumor progression, were highly expressed in PBMCs from RTP patients." (PMID 34687295, 2021). "Once activated, Smad2/3 enter the nucleus and regulate the expression of various molecules including NKG2D, CD71, CD98 with the ultimate effects of altering glucose uptake, cytokine production, and tumour killing." (PMID 33815694, 2021). "Each tissue was further separated into six specimens and analysed by both PESI-MS and immunohistochemistry (IHC) for p-SMAD2, a conventional examination to evaluate activation of TGF-β signalling and identify HNSCC cells stimulated with TGF-β within a tumour tissue." (PMID 32020064, 2020). "Here, we revealed the underlying mechanism of IL-1β-promoted tumor cell stemness by studying BMP1/5/8 and ID1 signaling pathway, but not TGF-β/Smad2/3 signaling pathway." (PMID 32547321, 2020). "Previous studies have demonstrated that miR-484 can reduce the expression of a series of oncogenes, such as ZEB1, SMAD2, etc., inhibit the epithelial-mesenchymal transition (EMT) of tumor cells, or regulate the extracellular signal-regulated kinase 1/2 signaling." (PMID 32192507, 2020). "However, according to recent studies, Smad3—a tumor-promoting factor—can increase VEGF expression and promote tumor angiogenesis, and Smad2—a tumor-suppressing factor—can inhibit tumor metastasis and angiogenesis." (PMID 32993787, 2020). "Altered status of SMAD2 may lead to an interrupt signaling of TGF-β, thus tumor cells can escape the growth inhibiting effect of TGF-β." (PMID 33202380, 2020). "Evaluation of tumor sections harvested from mice at day 14 (one day post-LY treatment) demonstrated reduced phosphorylation and nuclear translocation of the TGFβ signaling mediator, Smad2, indicating ALK5 signaling was attenuated in tumor tissue, specifically in the CD8α+ cells." (PMID 32273499, 2020). "In summary, miR-132 acts as a tumor suppressor and exerts a substantial role in inhibiting the proliferation, invasion, and enhanced the chemosensitivity to CDDP of OSCC via regulating TGF-β1/Smad2/3 signals in vitro." (PMID 31906769, 2020). "Mechanistic studies indicated that YFTL could suppress the angiogenesis and the epithelial-mesenchymal transition (EMT) of the tumor through Akt/ERK1/2 and TGFβ1/Smad2 pathways." (PMID 30781674, 2019). "These bioinformatics results implicate that SMAD2, SMAD3 and SMAD4 may exert tumor suppressive functions in the prostate, including the inhibition of ETV1’s oncogenic activity." (PMID 31160676, 2019). "Besides, SPRY2 has also been identified as a crucial negative regulator of multiple tumor-driving signaling pathways, such as ERK1/2, Smad2 and EGFR pathways." (PMID 30837325, 2019).
tumor (continued). "Nevertheless, canonical p-Smad2 was largely repressed in OSCC tumor tissues, suggesting that the activin A-mediated noncanonical pathway is essential for the carcinogenesis of OSCC." (PMID 30914776, 2019). "The TGF-β/Smad2/3 signaling pathway plays critical roles in cancer cell behavior through the unique TGF-β serine-threonine kinases and exerts both tumor suppressor and promoter activity in tumor progression and invasion." (PMID 31608236, 2019). "The tumor-growth stimulatory effects of MSC are mediated by TGF-β receptor and SMAD2 protein." (PMID 31842336, 2019). "According to the RISH and IHC analyses, the tumor from the MDNP/dCas9–miR‐524‐treated mice exhibited remarkably higher miR‐524 expression level, which led to significant inhibition of the expression of Smad2, Hes1, and Tead1." (PMID 30643726, 2019). "CCL7 activates the TGF-β pathway by enhancing Smad2 phosphorylation, and blocking the TGF-β pathway markedly inhibits the effects of CCL7 on tumor migration and invasion, highlighting the role of CCL7 in regulating tumor progression by influencing the tumor microenvironment via the TGF-β pathway." (PMID 29915688, 2018). "The binding of Smad2 or Smad3 and VEGF-C promoter was demonstrated in tumor cells." (PMID 30142879, 2018). "Correlating with earlier results showing that M7824mut does not accumulate in the tumor, M7824mut did not reduce intratumoral SMAD2 signaling." (PMID 29721396, 2018). "In the absence of KLF5, the same SMAD2/3 pathway can cause PDAC cell apoptosis, which can repress tumor development." (PMID 29254283, 2017). "The effects of halofuginone against bone metastases are consistent with an inhibition of TGF-β signaling in vivo, as shown by the decrease of phosphorylated Smad2/3 in the nuclei of cancer cells, and a subsequent decrease of TGF-β-regulated prometastatic genes in tumor cells." (PMID 29156807, 2017). "Additionally, JPJD can upregulate the expression of E-cadherin and Smad2/3 in the cytoplasm and downregulate the expression of Vimentin, p-Smad2/3, and Snail in the orthotopic CRC tumor tissues." (PMID 28299321, 2017). "SMAD2/3 complex can also directly induce the transcription of some miRNAs, like miR-192 and miR-451, previously highlighted as markers of CRT response in different tumor models." (PMID 26934318, 2016). "Tumor xenografts treated with DMH2 for 24 h and 9 days showed activation of TAK1 and TGFβ signaling as demonstrated by an increase in phosphorylated TAK1 and Smad2 respectively." (PMID 27048361, 2016). "Previous studies have described other crucial genes targeted by OTUB1, such as SMAD2/3, ERα and c-IAP2, that could promote tumor progression." (PMID 27167337, 2016). "Herein, the possible correlation between ALK5 full length (ALK5-FL) and ALK5-ICD protein, phosphorylated Smad2/3 (pSmad2/3), and expression of TGF-β target gene PAI-1, was investigated in a clinical ccRCC material, in relation to tumor grade, stage, size and cancer specific survival." (PMID 27166254, 2016). "SMAD2 and SMAD3 have distinct transcriptional roles in the tumor." (PMID 26146544, 2015). "However it has been demonstrated extensively that autophagy mediates tumor survival by supplying nutrients to stressed cancer cells, and promotes cancer invasion through the TGF-β/Smad2/Smad3 signaling pathway." (PMID 25980495, 2015). "As expected, phosphorylated Smad2 and Smad4 were detected in the untreated tumors (OVA + tumor)." (PMID 26076663, 2015). "However, neither FaDu cells with silenced KLK6 expression nor HeLa cells with ectopic overexpression exhibited obvious changes in SMAD2/3 phosphorylation, questioning a major impact of KLK6 on canonical TGF-β signaling, at least in mucosal tumor cells." (PMID 25990935, 2015). "In fact, SMAD2 knock-down cells demonstrated slightly higher baseline rates of cell proliferation, consistent with the role of the TGF-β/SMAD pathway in cell cycle arrest and tumor suppression." (PMID 25658089, 2015).